ERCC6L (ERCC excision repair 6 like, spindle assembly checkpoint helicase)
Diseases named in the same sentence as ERCC6L in open-access papers (continued):
Sharing a sentence is not in itself a finding about the gene and the disease.
tumor (continued). "Protein levels of ERCC6L were assessed in 85 LUAD tissue pairs via IHC, revealing significantly higher levels in tumor tissues compared to peritumoral lung tissues." (PMID 40691138, 2025). "Surprisingly, an increase in ERCC GSVA scores displayed a positive tendency toward the activation of the cell apoptosis pathway, which is contradictory to experimental evidence that inhibition of ERCC1, ERCC6L, or ERCC8 promotes apoptosis of tumor cells." (PMID 39582530, 2024). "ERCC6L, AHR and KIF2C downregulation were found to be potential mechanism of anti-tumor property of esketamine." (PMID 37968758, 2023). "In CRC, ERCC6L is significantly elevated in tumor tissues, and functions importantly in CRC cell growth, describing ERCC6L as a target for CRC." (PMID 34425559, 2021). "In the current study, we evaluated the expression of ERCC6L in HCC patients and demonstrated that ERCC6L levels were overexpressed in the tumor tissues than in paired tumor-adjacent tissues." (PMID 32891122, 2020). "To investigate the clinical significance of ERCC6L expression in patients with HCC, we examined its expression in a human HCC tissue array consisting of 90 paired HCC and tumor-adjacent tissues by IHC." (PMID 32891122, 2020). "ERCC6L was localized in the cytoplasm of HCC cells, and its expression was evidently higher in tumor tissue than in adjacent tissues (p < 0.05)." (PMID 32891122, 2020). "As a coactor of ERCC6L, PLK1 has been well known as a genetic marker of tumor cell proliferation." (PMID 28178669, 2017). "The ERCC6L and MYB genes could serve as prognostic markers by strengthening the link between lactylation modification and M2 polarization, offering a new target for anti-tumor strategies aimed at the “lactate metabolism-macrophage polarization” axis." (PMID 40672391, 2025). "Moreover, ERCC6L knockdown resulted in decreased levels of SOX2 and OCT4 in tumor tissues." (PMID 40691138, 2025). "Nonetheless, the role of ERCC6L and KIF4A in tumor progression remains unclear." (PMID 37667329, 2023). "Tumor growth significantly decreased by approximately threefold upon HIF-1α knockdown, with no further reduction observed with ERCC6L knockdown in HIF-1α-depleted xenografts, suggesting convergence of ERCC6L and HIF-1α mechanisms in this context." (PMID 40691138, 2025).
infection (1 paper, 2023). The state of being infected such as from the introduction of a foreign agent such as serum, vaccine, antigenic substance or organism. "BC cell lines MCF-7 and T47D stably overexpressing ERCC6L protein were constructed by infection with pHBLV-ERCC6L lentivirus (named MCF7 ERCC6L and T47D ERCC6L, respectively)." (PMID 37667329, 2023).
ERCC6L also shares sentences with these, for which no sentence is quoted: Bloom syndrome (2 papers); colorectal cancer (2); renal cell carcinoma (2); acquired aplastic anemia (1); Burkitt lymphoma (1); esophageal squamous cell carcinoma (1); Fanconi anemia (1); hematological disorders (1); Hepatic hemangioma (1); lentivirus infection (1); lymphoid neoplasm (1); lymphoma (1); non-Hodgkin B-cell lymphoma (1); non-small cell lung adenocarcinoma (1); oral cancer (1); pheochromocytoma-paraganglioma (1); prostate carcinoma (1); sarcoma (1); sarcopenia (1); Seckel syndrome (1); uveal melanoma (1); virus infection (1).